CRP (C-reactive protein)
Diseases named in the same sentence as CRP in open-access papers (continued):
Sharing a sentence is not in itself a finding about the gene and the disease.
bacterial infection (continued). "Anti-IL-6 neutralizing antibodies have been previously found in four patients with severe staphylococcal and bacterial infections and no increase in serum CRP." (PMID 40977713, 2025). "As a nonspecific biomarker of inflammation, C-reactive protein (CRP) indicates probable bacterial infection." (PMID 39997008, 2025). "In addition, plasma IL-1β and IL-6 were largely elevated in lactating sows by dietary intake of fish oil in the current study, which may be caused by the increase in MDA production instead of bacterial infection, as plasma CRP in lactating sows was not significantly influenced by fish oil intake." (PMID 40005899, 2025). "C-reactive protein (CRP) is an inflammatory marker that is often elevated during acute infections and has been studied for de-escalation purposes, but it is even less specific for bacterial infection than procalcitonin." (PMID 40426534, 2025). "Studies have reported that procalcitonin and CRP can be used to identify bacterial infections, although there are no specific clinical cutoff values for their use." (PMID 41303741, 2025). "CRP, a non-specific marker of inflammation, can be indicative of a bacterial infection and has shown potential to steward antibiotic usage in Southeast Asia." (PMID 40340660, 2025). "This explains why CRP usually is a marker of severe bacterial infection, but not of active lupus, in patients with SLE." (PMID 40632603, 2025). "Among the considered biomarkers that indicate infectious complications, only PCT may serve as a reliable indicator compared to CRP and WBC on days 1, 4, and 7 for culture-positive bacterial infections." (PMID 41007066, 2025). "PCT is not a biomarker specific to bacterial infection, and its lack of superiority over CRP has led to NICE guidelines not recommending its routine use in the UK." (PMID 41149760, 2025). "The diagnosis of FD was reconsidered because of persistent severe headaches and elevated C-reactive protein (CRP) that was not explained by a bacterial infection or any other inflammatory condition." (PMID 41323639, 2025). "In patients infected with covid-19, even previously useful tests (such as C-reactive protein) were found to be non-specific and unhelpful to differentiate them from a bacterial infection." (PMID 40375083, 2025). "Serial CRP measurements that remain within the normal range have an almost 100% negative predictive value for bacterial infection and can therefore be safely used to support early discontinuation of unnecessary antibiotic therapy." (PMID 41433251, 2025). "Bacterial infection was ruled out by a thorough clinical examination, negative blood cultures, and other negative infective markers like C-reactive protein (CRP) and procalcitonin." (PMID 40765595, 2025). "Therefore, it is a valuable biomarker for bacterial infections, showing greater specificity and sensitivity than other inflammatory markers like CRP and WBC, and it helps distinguish bacterial infections from other complications." (PMID 41007066, 2025). "Additional diagnostic testing, including inflammatory markers and thyroid studies, demonstrated normal C-reactive protein, erythrocyte sedimentation rate, and procalcitonin levels, indicating no systemic inflammation or bacterial infection." (PMID 41503320, 2025). "Although bacterial infection was not the primary consideration, empirical antibiotics were initially prescribed due to the patient’s systemic inflammatory response (CRP 96.6 mg/L)." (PMID 41137318, 2025). "CRP values can be monitored, and normal CRP values indicate the absence of bacterial infection, allowing clinicians to safely discontinue antibiotics." (PMID 40970024, 2025). "PSP showed a moderate positive correlation with CRP (r = 0.656; p < 0.001) and a stronger correlation with PCT (r = 0.601; p < 0.001), suggesting that PSP tracks closely with PCT, which is highly specific for bacterial infections." (PMID 40217689, 2025).
bacterial infection (continued). "The time of CRP elevation maybe advance and the magnitude of the elevation increases when MPP is combined with bacterial infection." (PMID 40171163, 2025). "The most used blood-based biomarker is CRP; however, it is not bacterial infection-specific and substantial elevations occur with other inflammatory or infectious causes." (PMID 41149760, 2025). "Unlike CRP, which can be elevated in non-infectious inflammatory conditions, nCD64 expression is more specific to bacterial infections." (PMID 39429998, 2024). "C-reactive protein (CRP) is elevated in more than 90% of acute spondylodiscitis cases and is a sensitive marker for bacterial infection; moreover, is considered the most specific marker for treatment response, as it returns to normal levels rapidly after successful treatment." (PMID 39595132, 2024). "In addition, OPG correlated well with CRP (rho = 0.428, p = 0.0011), ESR (rho = 0.3, p = 0.026), and WBC (rho = 0.266, p = 0.05) only in the group with bacterial infection." (PMID 38509997, 2024). "The performance of calprotectin in the detection of bacterial infections (AUC (95% CI): 0.804 (0.691, 0.916)) was comparable to the performance of both PCT (0.901 (0.823, 0.980)) and CRP (0.859 (0.764, 0.953)) and superior to the WBC count (0.684 (0.544, 0.823))." (PMID 38786153, 2024). "Most of the health care providers in this study performed additional diagnostic tests before prescribing antibiotics, but the majority of those tests, such as chest X‐ray and CRP, did not differentiate between viral and bacterial infection." (PMID 38497844, 2024). "Comparison of median parameters (NLR, PLR, ANC, PCT, CRP) between bacterial infections and non-infectious diseases." (PMID 39296886, 2024). "During HAdV infections, increased C-reactive protein (CRP) and procalcitonin, white blood cells, and neutrophilic shift may mimic bacterial infections." (PMID 39377906, 2024). "The laboratory test results of MPP group and RMPP group patients showed that the CRP, PCT, IL-6, and incidence of concurrent bacterial infections in MPP group patients were lower than those in RMPP group patients, and the difference was statistically significant." (PMID 39809213, 2024). "Such tools may be effective at detecting a bacterial infection, for example an RCT of CRP point-of-care tests saw a 20% absolute reduction in patient-reported antibiotic consumption over four weeks." (PMID 38507232, 2024). "The 27 patients with bacterial infections had strongly increased CRP, whereas adiponectin levels did not change in comparison to the 37 non-infected patients." (PMID 38791005, 2024). "Initial blood tests showed elevated levels of CRP (15.3 mg/dl; IQR 8.8–21.3), PCT (0.36 ng/ml; IQR 0.13–0.89), and D-dimer (2.7 μg/ml; IQR 1.3–7.1) in the Omicron group, which are affected by complications of bacterial infection." (PMID 38374034, 2024). "Serum PCT and CRP levels in COVID‐19 patients with bacterial coinfection are higher than those without bacterial infection." (PMID 39692539, 2024). "The subgroup with limited CRP response included younger patients with more negative blood cultures, with mean estimates likely reduced by the absence of bacterial infection or a systemic response in a substantial subset." (PMID 38599549, 2024). "Levels of CRP increase in response to inflammation, infection, or injury and are generally raised in bacterial infections, but not in viral infections." (PMID 39192993, 2024). "CRP and PCT are biomarkers commonly used to detect bacterial infections in their early stages." (PMID 38633749, 2024). "In Group B, serum C-reactive protein and the proportion of patients with purulent sputum increased with placebo (suggesting bacterial infection), but not with SNG001." (PMID 38811970, 2024). "It should be noted that the CRP (p = 0.832) and procalcitonin (p = 0.767) of patients with and without bacterial infections were similar." (PMID 38255230, 2024).
bacterial infection (continued). "We intentionally chose a lower CRP cut-off for antibiotic prescription (40 mg/l) than what was used in the Tanzanian study (80 mg/l) to favor sensitivity for bacterial infection over specificity as the CHW are not formally medically trained." (PMID 39159269, 2024). "In meta-analysis, it was reported that procalcitonin performs better than leukocyte count and C-reactive protein for detecting serious bacterial infection among children with fever without source aged between 7days and 36 months." (PMID 36670711, 2023). "A meta-analysis found a specificity of PCT for bacterial infection of 81% (95% CI, 67–90%) compared to that of 67% (95% CI, 56–77%) for CRP and found a sensitivity of PCT of 88% (95% CI 80–93%) compared to that of 75% (95% CI, 62–84%) for CRP." (PMID 37239067, 2023). "Our results do not support the applicability of PCT or CRP testing to indicate the emergence of bacterial infection in the ICU population." (PMID 37107071, 2023). "The greatest reduction in the use of antibiotics was observed in group 2, consisting of children with a wheeze or runny nose and no fever, or those with a CXR or blood test results not indicative of bacterial infection (ANC < 5 × 109/L or CRP < 10 mg/L)." (PMID 37488633, 2023). "The parameters highlighted in the comparison of cases with or without bacterial infection are almost the same as those comparing positive or negative test apart from the CRP value." (PMID 37110306, 2023). "Since then, it is known to increase with the severity of bacterial infection, and unlike C-reactive protein, it is rarely affected by the glucocorticoid level." (PMID 37623446, 2023). "Procalcitonin (PCT) is a blood test which is specific for bacterial infection and responds more quickly than CRP, but it is not routinely used in NHS." (PMID 37254156, 2023). "Interestingly, the biomarkers for bacterial infections (WBC, CRP, and PCT) were markedly increased in RV-positive children in our study." (PMID 37009280, 2023). "We were not able to include procalcitonin, considered a better marker than CRP for bacterial infections as it was not available in our institution during the study period." (PMID 37814760, 2023). "While other biomarkers for bacterial infection such as procalcitonin (PCT) and absolute neutrophil count (ANC) are available, CRP was used in our study due to its cost-effectiveness and swift test result confirmation compared to PCT and ANC, making it useful for acute infection." (PMID 37876732, 2023). "Studies have shown that using a CRP cut-off > 80 mg/L to rule in a bacterial infection and a CRP cut-off < 20 mg/L to rule out bacterial infections is reliable with >80% sensitivity and >90% specificity." (PMID 37371198, 2023). "The CRP level is an acute phase reactant that represents the inflammation level and is not specific for diagnosing bacterial infections." (PMID 37144031, 2023). "The medical group had a lower average CRP than the surgical NEC 2 days after diagnosis, which may suggest an adequate response to antibiotic treatment, resolution of bacterial infection, and decreased inflammation." (PMID 36670710, 2023). "Chemerin in plasma correlated with C-reactive protein and leukocyte count but not with procalcitonin, a clinical marker of bacterial infection." (PMID 37509420, 2023). "Normal CRP values in serial controls within a few days from symptom onset are considered indicative of the absence of a bacterial infection." (PMID 37627653, 2023). "Consequently, CRP and WBC counts are insufficient at either ruling in or ruling out bacterial infections in comparison to other inflammatory diseases." (PMID 36915043, 2023). "Infectious diseases are associated with higher CRP than non-infectious conditions, and bacterial infections are accompanied by higher CRP concentrations compared to non-bacterial infections." (PMID 36865442, 2023). "suPAR, rather than C-reactive protein (CRP) has been proposed as a biomarker for bacterial infection." (PMID 36766787, 2023).
bacterial infection (continued). "CRP is in widespread clinical use as a general marker of inflammation but not specific for bacterial infections." (PMID 35164633, 2022). "CRP was negative in seven patients (17.5%), three of them with a confirmed bacterial infection; PCT was negative in four patients (10%), none of them had a confirmed bacterial infection." (PMID 35329889, 2022). "During inflammatory condition, such as viral or bacterial infection, there comes to a rapid increase of pro-inflammatory markers such as interleukin 4 (il-4), interleukin 6 (il-6), tumor necrosis factor (TNF) and C reactive protein (CRP)." (PMID 35431842, 2022). "In addition to complete blood count, acute phase proteins such as CRP and PCT are useful markers of viral and bacterial infections." (PMID 36430240, 2022). "A single CRP measurement, especially when low, can mislead the clinicians to rule out a bacterial infection." (PMID 35897672, 2022). "In the present study, the median CRP concentration of 88.9 mg/L (1.4–192.7 mg/L) was not as high as in other diseases with bacterial infection." (PMID 36713872, 2022). "We also reviewed the correlation of cytokines with CRP and PCT in order to assess whether they will equally assist in identifying bacterial infections." (PMID 35500008, 2022). "In patients admitted to the ICU with H1N1vIPN, PCT is a sensitive marker with a good negative predictive value for detecting bacterial infection and is superior to CRP." (PMID 35055399, 2022). "In this study, we found that IL-10 had some predictive effect on bacterial infection and respiratory bacterial infections, but its AUC did not have a strong advantage over body temperature, CRP, and PCT." (PMID 35463642, 2022). "As we know, CRP and PCT are regarded as specific biomarkers for bacterial infection." (PMID 35733094, 2022). "In febrile children with a confirmed bacterial infection and who were tested negative with mRDT-PfHRP2 (n = 19), there were 14 cases who were tested CRP positive and 5 were tested CRP negative." (PMID 36536340, 2022). "There were 22 cases of confirmed non-bacterial infection of whom 14 were tested mRDT-PfHRP2 negative but CRP positive and 8 who were tested negative for both RDTs." (PMID 36536340, 2022). "In ancient Limulus, which survives without the benefits of adaptive immunity, CRP is vital for host defense against bacterial infection." (PMID 35407379, 2022). "The elevated CRP is not related to the amount of bleeding, operation time, drugs, age and gender, but is related to the bacterial infection, the type and degree of tissue damage." (PMID 36684362, 2022). "CRP is one of the classical acute-phase proteins, which could increase significantly at the early stage of IFI and bacterial infection." (PMID 35740137, 2022). "CRP velocity did not significantly improve CRP performance to diagnose bacterial infections in NICU patients- area under the ROC curve of 0.75 for CRP vs. 0.77 for CRP velocity." (PMID 36517750, 2022). "Procalcitonin (PCT) is a biomarker more specific for bacterial infection and responds quicker than other commonly used biomarkers such as C reactive protein, but is not routinely used in the National Health Service (NHS)." (PMID 35078830, 2022). "At a subgroup analysis,we found that mean CRP in these patients with “possible bacterial infection was higher than in patients with no bacterial infection, but the overall performance of CRP was relatively poor." (PMID 36517750, 2022). "CRP is a nonspecific biomarker of inflammation that also increases during bacterial infections, being an acute-phase response protein." (PMID 36143057, 2022). "CRP velocity decrease over time was similar in bacterial vs. non-bacterial infections: 35-fold (±62) for bacterial infections vs. 34.5-fold (±88) for non-bacterial infections (p = 0.9)." (PMID 36517750, 2022). "Patients with bacterial infections commonly present significantly higher CRP levels than those without." (PMID 36443747, 2022).
bacterial infection (continued). "This study indicated that male patients had higher levels of inflammatory markers (including CRP, SAA, FIB), suggesting that bacterial infection is more common in male patients and might aggravate the disease progression." (PMID 34230921, 2021). "The potent and long-lasting anti-inflammatory effects of dexamethasone and tocilizumab appear to directly attenuate PCT and CRP to such extent that they are no longer sufficiently induced in response to bacterial infection." (PMID 34353339, 2021). "C-reactive protein is a non-specific acute phase protein that is elevated in both viral and bacterial infections and MxA is elevated in acute viral infections." (PMID 34703832, 2021). "Determining the levels of D-dimer, CRP, ESR, and other inflammatory biomarkers is essential to detecting bacterial infection in the lungs, and may help preliminarily evaluate patients’ immune status." (PMID 33914805, 2021). "In contrast, CRP is more stable with a half-life of 18-20 hours and has become the most commonly used biomarker for bacterial infection and inflammation and is routinely measured in the clinic nowadays for both children and adults." (PMID 34079538, 2021). "Combining WBC, NEUT, CRP, PCT, IL-6, and IFN-γ in a bioscore system may result in faster prediction of bacterial infections in SLE and may guide toward a more appropriate, timely treatment for SLE." (PMID 33732661, 2021). "CRP obviously mediates important immune defense mechanisms, which should not be suppressed during an ongoing bacterial infection." (PMID 34408751, 2021). "Despite this, use of PCT in the UK is uncommon, and for routine management of bacterial infection, it is not thought to provide any additional benefit over more traditional biomarkers (e.g., CRP)." (PMID 34572701, 2021). "Among our patient population, despite the clinical picture corresponding to serious bacterial diseases, laboratory tests (CRP, PCT and morphology) did not deviate significantly from the standards." (PMID 33548163, 2021). "Regarding ICU patients without secondary bacterial infection median PCT levels were 0.5 (IQR 0.3–2.4) while CRP was considerably elevated (155.8, IQR 78.8–204.6)." (PMID 34021897, 2021). "Although C reactive protein (CRP) and procalcitonin are currently used as markers for bacterial infections, they measure non-specific inflammation and immunological responses." (PMID 33208397, 2021). "Compared with CRP, PCT showed a stronger suggestive effect on the severity of bacterial infection." (PMID 33791046, 2021). "While procalcitonin levels are generally normal because of the absence of a bacterial infection, high CRP level is a common finding." (PMID 33501850, 2021). "Using C-reactive protein (CRP), a non-specific marker of infections, or procalcitonin, a more specific marker of bacterial infections, to guide the decision of antibiotic treatment is not recommended for exacerbations of COPD." (PMID 33616876, 2021). "This is consistent with the epidemiologic change that has occurred since WHO radiographic scoring was developed; so PEPC or elevated CRP should no longer be considered a proxy for bacterial infection." (PMID 34388194, 2021). "White blood cell count, C-reactive protein and procalcitonin are most often used to diagnose bacterial infections, while there are no established markers for viral infections." (PMID 34142256, 2021). "Combining WBC, NEUT, CRP, PCT, IL-6, and IFN-γ in a bioscore system may result in a faster prediction of bacterial infections in SLE and may guide toward a more appropriate, timely treatment for SLE." (PMID 33732661, 2021). "Third, blood measures of acute phase reactants suggestive of bacterial infection such as procalcitonin or CRP were not systematically performed, and should be assessed in future trials." (PMID 33649379, 2021). "C-Reactive Protein (CRP) is a non-specific biomarker of inflammation, which gives an indication of likely bacterial infection." (PMID 34748558, 2021).